IFNG (interferon gamma)
Diseases named in the same sentence as IFNG in open-access papers (continued):
Sharing a sentence is not in itself a finding about the gene and the disease.
tuberculosis (continued). "Tuberculosis triggers a robust immune response that involves the release of key pro-inflammatory cytokines, including tumor necrosis factor-alpha, interleukin-1, interleukin-6 (IL-6), interferon-gamma (IFN-γ), and interleukin-12 (IL-12)." (PMID 39941433, 2025). "However, positive tests for tuberculosis (e.g., purified protein derivative test or interferon-gamma release assays) or syphilis (e.g., fluorescent treponemal antibody absorption test) will indicate an infectious etiology." (PMID 40002713, 2025). "An additional definition of therapeutic vaccination in the context of tuberculosis is the administration of a vaccine to individuals with signs of M. tuberculosis exposure, such as a positive interferon-gamma release assay (IGRA + ve), to prevent the progression to active tuberculosis." (PMID 41226364, 2025). "Additionally, we evaluated four PPD brands, including those used for skin testing, in the Bovine Tuberculosis Interferon Gamma Test (IFN-γ test) measuring IFN-γ induction in whole blood." (PMID 38431678, 2024). "Furthermore, NO2 can weaken the immune system by inducing the production of tumor necrosis factor alpha (TNF-α) and interferon gamma (IFN-γ), thereby increasing the susceptibility to tuberculosis." (PMID 39765608, 2024). "The tuberculosis (TB) diagnosis involves various methods, such as microscopic examination, culture-based methods, molecular techniques, chest X-rays, serological tests, and interferon-gamma release assays." (PMID 39092361, 2024). "IL-6, IP-10, IL-10, and IL-22 were detectable in the majority of tuberculosis patients (> 50%), whereas IFNγ and GM-CSF were measurable only in minor subsets of both study groups (IFNγ: 41.1% in patients, 25.0% in contacts; GM-CSF: 21.4% in patients, 2.5% in contacts)." (PMID 35759173, 2023). "In this study, it was shown that neutralizing anti-IFNγ auto-antibodies that were present in 10 out of 30 HIV-negative tuberculosis (TB) patients, with the highest antibody titers found in patients with advanced disease, and those with detectable IFNγ in serum." (PMID 38203686, 2023). "Although interferon-gamma release assays (IGRAs) have been shown to be valid methods for identifying M.tb infection and auxiliary methods for diagnosis of active tuberculosis (TB), lower sensitivity and higher indeterminate rate were often detected among immunosuppressed patients." (PMID 35432271, 2022). "Interferon-gamma releasing assay is a test used widely for screening tuberculosis." (PMID 35198325, 2022). "In light of published evidence associating IFNγ and IL10 with the severity of parasitic infection and tuberculosis, we investigated whether IFNγ/IL10 reflects the pathogen burden of immune cells when challenged with typical pathogens found in sepsis." (PMID 33767693, 2021). "Furthermore, the gene at the 3′ end of the deletion, Rv2628, is associated with latent tuberculosis infection as shown by a stronger cumulative interferon-gamma response towards Rv2628 antigens, compared to tuberculosis-positive individuals." (PMID 33575588, 2020). "Consequently, patients with tuberculosis (TB) displaying the most severe expression of the disease produce the lowest amounts of IFNG against the pathogen." (PMID 31616423, 2019). "Moreover, we have reported that the IFNG rs1861494 single nucleotide polymorphism (SNP) would act as a biomarker of resistance to tuberculosis in the Argentinean population, since it affects the secretion of IFNG." (PMID 31616423, 2019). "Whether the low IFNγ+ T-cell responses induced by MVA85A could be sufficient to protect against tuberculosis before BCG administration is unknown." (PMID 29028973, 2018). "Also, the introduction of interferon gamma tests like Quantiferon helped to confirm the diagnosis of tuberculosis." (PMID 28070744, 2018).
tuberculosis (continued). "Furthermore, among others, SNPs in Interleukin 1β (IL1B), IL12, IFNG, Interleukin 10 (IL10) and Tumor Necrosis Factor α (TNFα) genes were described in relation with risk to tuberculosis disease." (PMID 29361774, 2018). "To date, only two reports in the Argentinean population have analyzed the association between a cytokine SNP and tuberculosis, but no one in the IFNG gene, a crucial cytokine for controlling Mtb infection." (PMID 29361774, 2018). "Interestingly, they also demonstrated that IL-17 and SLAMF1 have opposing effects on IFNγ production in tuberculosis patients." (PMID 29434592, 2018). "In case of HIIS additional specifications included a CD4+ lymphocyte count ≥200/mm3 and a positive T-cell function (via analyzable positive control of a standard tuberculosis interferon-gamma-release-assay (TB-IGRA) indicating mitogen-induced T cell proliferation)." (PMID 29499726, 2018). "However, patients with prior active TB, prior exposure to active tuberculosis or history of positive TST or interferon-gamma release assay IGRA tests are recommended to be evaluated for active tuberculosis." (PMID 29717163, 2018). "The diagnostic values of interferon-gamma release assays (IGRA) in tuberculosis (TB) vary a lot with different site of infections, with especially higher sensitivities in chronic forms of TB such as tuberculosis of the lymph node." (PMID 28413722, 2017). "Likewise, interferon gamma release assays like QuantiFERON TB Gold is an important test but have significant limitations and cannot distinguish between latent and active tuberculosis." (PMID 28101723, 2017). "In the population under surveillance (N = 6100), using an interferon-gamma release assay followed by rifampin was dominant compared to the base case, preventing 4.90 cases of tuberculosis, a 4.9% reduction, adding 4.0 quality adjusted life years, and saving $353,013 over the ensuing ten-years." (PMID 29084227, 2017). "General advice on methodology for such studies exist and an assessment of how they have been implemented in the case of point of care testing strategies for active tuberculosis and for interferon-gamma release assays for latent TB infection have been published." (PMID 26954678, 2016). "This may be due to patients with active tuberculosis showing suppression of the interferon-gamma release response by M. tuberculosis by increased activity of regulatory T-cells." (PMID 27433370, 2016). "It is believed generally that IFNG plays a key role in the pathogenesis of tuberculosis." (PMID 26649196, 2015). "The activity of regulatory T cells may not only dampen immunogenicity and protective efficacy of tuberculosis-vaccines, but also hamper diagnosis of infection of tuberculosis, when using immune (e.g. IFNγ-release) assays." (PMID 24714620, 2014). "Interferon-gamma release assays (IGRAs) have proven to be useful to accurately detect Mycobacterium tuberculosis (Mtb) infection, but they cannot reliably discriminate between active tuberculosis (TB) and latent tuberculosis infection (LTBI)." (PMID 24244502, 2013). "The phase change-based incubation method we describe has already been used for performing interferon gamma release assays for tuberculosis in resource-limited settings, and could have an array of uses in such areas." (PMID 23853696, 2013). "The utility of T-cell based interferon-gamma release assays for the diagnosis of latent tuberculosis infection remains unclear in settings with a high burden of tuberculosis." (PMID 21483746, 2011). "Interferon gamma (IFN-γ) release assays (IGRA) based on the in vitro T cell responses to Mycobacterium-tuberculosis (MTB)-specific antigens have the potential to improve the diagnosis of tuberculosis (TB)." (PMID 20507549, 2010). "T-cell interferon-gamma release assays (IGRAs) may have a role in the diagnosis of active tuberculosis when evaluating patients for whom standard microbiology has limited sensitivity." (PMID 20302657, 2010).
tuberculosis (continued). "Incidence of active tuberculosis in household contacts and IFNγ production levels at baseline." (PMID 20011589, 2009). "However, a significant trend for tuberculosis development amongst high HHC IFNγ producers was observed (trend Log rank p = 0.007)." (PMID 20011589, 2009). "We estimated the prevalence of M. tuberculosis infection by IGRA and TST in HHCs and their source population (SP), and assessed whether IFNγ levels in HHCs correlate with tuberculosis development." (PMID 20011589, 2009). "Moreover, application of IFNγ by aerosol is able to activate alveolar macrophages in human beings and shows therapeutic potential in tuberculosis patients." (PMID 18801189, 2008). "Higher production of IFNγ relative to IL-10 in P3 may reflect Mtb-specific immunological memory as a consequence of previous tuberculosis." (PMID 18442415, 2008). "Moreover, inhalation of IFNγ has already been suggested for the treatment of tuberculosis and appears to show clinical efficacy." (PMID 18801189, 2008). "A positive interferon-gamma release assay raised suspicion for latent tuberculosis (TB), and empirical anti-TB therapy was commenced." (PMID 41322995, 2025). "Some biochemical indicators, such as tuberculosis interferon-gamma release assays (TB-IGRA), pleural effusion adenosine deaminase (pADA), pleural effusion lactate dehydrogenase (pLDH), the pLDH/pADA ratio, and pleural effusion cytological categorization, may serve as auxiliary diagnostic markers." (PMID 40757203, 2025). "Screening for tuberculosis infections (TBI) using the tuberculin skin test or interferon-gamma release assays (IGRA) is crucial in controlling the global TB burden." (PMID 40032785, 2025). "Among this, CD4+ T lymphocytes are key players in defending against tuberculosis (TB), mainly by producing interferon-gamma (IFN-γ), a cytokine critical for activating macrophages and controlling infection by MTBC." (PMID 40990013, 2025). "Testing for tuberculosis, such as a tuberculin skin test or interferon-gamma release assays, and assessment for evidence of caseation necrosis in biopsy specimens, which is characteristic of tuberculosis but not of sarcoidosis, may also help in the differentiation." (PMID 39712766, 2024). "Preventive therapy, in particular with the drug isoniazid, may be indicated in patients with a previous history of active tuberculosis, contact with people with active, open tuberculosis, and patients with positive tuberculin skin test and /or interferon-gamma release assays (IGRA)." (PMID 38245786, 2024). "The results for tuberculosis (TB), interferon‐gamma (IFN‐Gamma), hepatitis C (HCV), hepatitis B (HBV), and human immunodeficiency virus (HIV) were negative." (PMID 39588247, 2024). "Interferon-gamma (IFN-γ) release assays play a pivotal role in tuberculosis infection (TBI) diagnosis, with QuantiFERON-TB Gold Plus—an enzyme-linked immunosorbent assay (ELISA)—among the most widely utilized." (PMID 38975791, 2024). "These EHR metrics primarily include age, hemoglobin, cough, weight loss, low-grade fever, calcification detected by computed tomography [CT calcification], and the interferon gamma release assay for tuberculosis [TB-IGRA]." (PMID 39185416, 2024). "Mycobacterium tuberculosis-specific IFNγ+CD4 T-cell responses in TB-IRIS patients are differentiated, highly activated, and potentially cytotoxic." (PMID 36726536, 2023). "Evidence on the comparative performance of purified protein derivative tuberculin skin tests (TST) and interferon-gamma release assays (IGRA) for predicting incident active tuberculosis (TB) remains conflicting." (PMID 36636295, 2023). "Thus, the antagonism of protective IFNγ and IL-1 responses by type I IFNs may be a key driver of progression to active tuberculosis." (PMID 38029747, 2023).
tuberculosis (continued). "IGRAs, including QuantiFERON-TB Gold In-Tube test (QFT-GIT), QuantiFERON-TB Gold Plus (QFT-plus), and T-SPOT.TB, are in-vitro blood tests detecting T-cell released interferon-gamma (IFN-γ) stimulated by M. tuberculosis antigen." (PMID 35668411, 2022). "In TB pathology, T cells produce IFNγ, which aids in protective immunity against M. tuberculosis by activating macrophages, allowing them to eliminate Mtb more effectively." (PMID 35401549, 2022). "T-SPOT.TB (T-SPOT) is widely used for the detection of Mycobacterium tuberculosis infection by detecting interferon-gamma (IFN-γ) release in T lymphocytes." (PMID 36093183, 2022). "In addition, interferon-gamma (IFN-γ) release assays (IGRAs) can be used to diagnose tuberculosis." (PMID 36204647, 2022). "As a result of this broad range of effect, interferon gamma has been utilized clinically as primary, adjunctive, and experimental treatment for a similarly broad array of other medical conditions, including cancer, tuberculosis, hepatitis, chronic granulomatous disease, and atopic dermatitis." (PMID 35309862, 2022). "Tuberculosis stratification could be further improved by the Mtb Ag:BCG IFNγ ratio." (PMID 33059361, 2021). "Blood is incubated in tubes coated with TB peptide antigens and interferon gamma is released from activated lymphocytes in patients who have previously been infected with Mycobacterium tuberculosis." (PMID 33919426, 2021). "Furthermore, some of these proteins may replace the purified protein derivative of M. tuberculosis in the specific diagnosis of tuberculosis by using interferon-gamma release assays and/or tuberculin-type skin tests." (PMID 33430286, 2021). "Recent research suggests that incorporation of novel Mycobacterium tuberculosis antigens expressed during different stages of TB [reviewed in] and the measurement of additional cytokines can improve performance of currently used interferon-gamma release assay." (PMID 33489933, 2020). "Investigation of 30 other workers in the same or adjacent offices with interviews, interferon-gamma release assays (IGRAs) and chest X-rays, identified one new TB case and latent tuberculosis infection (LTBI) in 40.0% (12/30) of the contacts." (PMID 32089146, 2020). "To find more evidence to support the diagnosis of tuberculosis, we arranged the tuberculosis antibody test, interferon-gamma release assay (T-SPOT.TB) and purified protein derivative test (PPD skin test) for the patient." (PMID 33287912, 2020). "Moreover, Mtb-Ag-stimulated PBMCs from TB carrying the C allele produced the lowest levels of IFNG, the highest level of IL17A, and the minimum proliferation indexes as compared to TT TB, suggesting a relationship between the C allele and tuberculosis severity." (PMID 31616423, 2019). "Early secretory antigenic target-6 (ESAT-6) is an immunodominant Mycobacterium tuberculosis (M.tb) antigen included in novel vaccines against tuberculosis (TB) and in interferon-gamma (IFN-γ) release assays (IGRAs)." (PMID 30668657, 2019). "The degree of reduction in IFNG production by peripheral blood mononuclear cells (PBMC) is a marker of disease severity in patients with tuberculosis (TB)." (PMID 29361774, 2018). "Such rapid detection makes it possible to identify differences between active tuberculosis and latent infection: more CD4+ T cells produced IFNG or TNFA mRNA as early as 2 h post-stimulation in active TB." (PMID 30283456, 2018). "The high background rates of positive results on the tuberculin skin test (TST) and interferon-gamma release assay (IGRA) sometimes confuse the investigation of tuberculosis (TB) contact in TB-prevalent countries, particularly in elderly contacts." (PMID 29505017, 2018). "Besides, IFNG secretion is lower in patients with the most severe manifestation of tuberculosis." (PMID 29361774, 2018). "Common variants of IFNG, such as IFNG +874 T/A(rs2430561), may be related to tuberculosis susceptibility, but this association has not been consistently observed." (PMID 28881572, 2017).
tuberculosis (continued). "In the stratified analysis by TB type, significant associations were found with both pulmonary tuberculosis (PTB) and extra-pulmonary tuberculosis (EPTB) risks and IFNG+874 T/A (rs2430561) polymorphism in the five genetic models." (PMID 28881572, 2017). "However, the risk of active tuberculosis disease following screening using interferon-gamma release assays in immigrants is not well defined." (PMID 27558397, 2016). "Because interferon-gamma (IFN-γ) plays a pivotal role in regulating cell-mediated immune response against TB, interferon-gamma release assays (IGRAs) were developed to detect Mycobacterium tuberculosis infection." (PMID 25938227, 2015). "However, interferon gamma releasing assay was positive for tuberculosis." (PMID 26083934, 2015). "Interestingly IL-27R-/- mice produce less IFNγ at sites of granuloma formation in tuberculosis mice models suggesting that IL-27 might similarly contribute to early stages of granuloma formation in sarcoidosis." (PMID 25386143, 2014). "Interferon-gamma release assays (IGRAs), such as the QuantiFERON-TB Gold In-Tube (QFT), are now available and use antigens that are more specific to M. tuberculosis than the TST." (PMID 24886359, 2014). "The methods are illustrated using simulated data and applied to the problem of estimating the incremental value of a novel interferon-gamma release assay (IGRA) over the tuberculin skin test (TST) for latent tuberculosis (TB) screening." (PMID 24886359, 2014). "IGRA uses specific antigens of Mycobacterium tuberculosis, such as early antigenic target-6 (ESAT-6), culture filtrate protein 10 (CFP-10), and TB 7.7, to stimulate whole blood to induce interferon-gamma production by antigen-specific T cells." (PMID 24454900, 2014). "The interferon-gamma (IFN-γ) releasing antigen-specific T cells have been extensively exploited in the immunodiagnostics of tuberculosis (TB)." (PMID 24308801, 2013). "Our findings highlight the importance of studying pulmonary immune-compartment M. tuberculosis specific responses to elucidate IFNγ secretion across the spectrum of TB disease." (PMID 22778764, 2012). "This immunological study of HIV-infected individuals from a high TB burden area reveals that M. tuberculosis antigen-specific IFNγ responses differ between the pulmonary and blood immunological compartments." (PMID 22778764, 2012). "Peripheral blood interferon-gamma release assays (IGRAs) have sub-optimal sensitivity and specificity for diagnosis of active pulmonary tuberculosis (TB)." (PMID 22745833, 2012). "The T-SPOT.TB (Oxford Immunotec Ltd, Abingdon, UK) is an interferon gamma release assay (IGRA) for detection of latent Mycobacterium tuberculosis infection (LTBI)." (PMID 22567274, 2012). "The most widely used TB immunodiagnostic tests, the interferon gamma (IFN-γ) release assays (IGRAs), have proven to be useful in the diagnosis of Mycobacterium tuberculosis (M.tb) infection especially in comparison to the tuberculin skin test (TST)." (PMID 22693640, 2012). "Cross-sectional study of one time use of an interferon-gamma release assay (T-SPOT.TB - immunospot) to detect tuberculosis infection in patients in a UK inner city HIV clinic with a large sub-Saharan population." (PMID 22558946, 2012). "Immunity to TB is dependent on the accumulation of IFNγ-producing T helper cell type 1 (Th1) in the lungs, subsequent activation of M.tuberculosis-infected macrophages and control of bacteria." (PMID 21249199, 2011). "Therefore, we quantified pulmonary IL-12 and IFNγ production during tuberculosis reactivation." (PMID 22132068, 2011). "The measurement of Interferon gamma or Interferon gamma inducible protein (IP)-10 in antigen stimulated blood samples is suggested as an alternative method for latent tuberculosis (TB) diagnosis." (PMID 20140219, 2010).